SMARCA4 (SWI/SNF related BAF chromatin remodeling complex subunit ATPase 4)
Diseases named in the same sentence as SMARCA4 in open-access papers (continued):
Sharing a sentence is not in itself a finding about the gene and the disease.
adenocarcinoma (44 papers, 2010 to 2025). A common cancer characterized by the presence of malignant glandular cells. "Positive nuclear staining of SMARCA2 and concomitant nuclear staining of SMARCA2 and SMARCA4 were both associated with better five-year survival in 300 NSCLC cases (150 adenocarcinoma and 150 SCC)." (PMID 39888726, 2025). "Loss of SMARCA2 and SMARCA4 was frequent in solid-predominant adenocarcinomas and tumors with low levels of bronchial epithelial markers, i.e., TTF-1, CK7, and E-cadherin." (PMID 39888726, 2025). "Typically, patients with SMARCA4-deficient NSCLC clinically present with adenocarcinoma, larger invasive tumor size, a smoking history, and fewer epidermal growth factor receptor (EGFR) mutations (p < 0.05)." (PMID 39063938, 2024). "The last SMARCA4 mutation analysis highlighted that the differences in all-cause mortality remained significant between the adenocarcinoma NSCLC patients that were mutated (N = 21) vs. wild-type (N = 204) (HR: 2.06; p = 0.003)." (PMID 39063938, 2024). "SMARCA4-deficient adenocarcinomas are preponderant in younger aged male smokers with a predominant solid morphology." (PMID 34440689, 2021). "We speculated the HNF4α expression in grade 3 adenocarcinoma may imply dedifferentiation associated with the inactivated SMARCA4 function, resulting in high-grade morphology and poor prognosis." (PMID 38710944, 2025). "Additionally, loss of SMARCA4 was more frequently observed in HNF4α-positive grade 3 adenocarcinomas (2/6, 33%)." (PMID 38710944, 2025). "Thus, it is paramount to identify the SMARCA4-deficient adenocarcinoma, as it carries worse repercussions on patient survival, despite having an exceptionally low prevalence." (PMID 34440689, 2021). "Moreover, an additional somatic mutation was also detected in neuroendocrine components of both primary and metastatic sites, while a missense mutation in SMARCA4 gene (p.Pro171Leu) was identified only in the adenocarcinoma component of primary site." (PMID 34926584, 2021). "HNF4α-positive adenocarcinomas(n = 33) were divided into two groups: the variant group(15 mucinous, 2 enteric, and 1 colloid), where SMARCA4 was retained in all cases, and the conventional non-mucinous group(6 papillary, 5 solid, and 4 acinar), where SMARCA4 was lost in 3/15 cases(20%)." (PMID 38710944, 2025). "SMARCA4-mutated patients tend to present with adenocarcinoma, a smoking history, and a low frequency of epidermal growth factor receptor (EGFR)/SMARCA4 co-mutations." (PMID 41007704, 2025). "Another patient, a 54‐year‐old male with no smoking history, was diagnosed with poorly differentiated adenocarcinoma with SMARCA4 deletion on June 25, 2022." (PMID 37184108, 2023). "The focus of this review is on SMARCA4-dNSCLC, which is prevalent in about 5–10% especially among the poorly differentiated adenocarcinomas." (PMID 34440689, 2021). "Note that, unlike HNF4α, loss of SMARCA4 was not an independent prognostic factor in grade 3 adenocarcinomas in our study (Online Resource 6), but we did not investigate the mutational status of SMARCA4 in SMARCA4-retained adenocarcinomas." (PMID 38710944, 2025). "Although the loss of SMARCA2 was not significantly more frequent in HNF4α-positive adenocarcinomas, two of the four HNF4α-positive Grade 3 adenocarcinomas that expressed SMARCA4 showed the loss of SMARCA2." (PMID 38710944, 2025). "Both the expression of HNF4α and the loss of SMARCA4 are considered characteristics of non-TRU-type adenocarcinomas, but their relationship remains unclear." (PMID 38710944, 2025). "The SMARCA4 (BRG1) subunit, as well as neuron-specific SWI/SNF subunits BAF53B, BAF45B, and CREST, are significantly overexpressed in NEPC compared to CRPC adenocarcinoma, thus positioning SWI/SNF as a regulator of lineage plasticity." (PMID 36212399, 2022).
adenocarcinoma (continued). "This study aimed to investigate the clinical relevance of immunohistochemical expression of proteins of the SWI/SNF complex, SMARCA2, SMARCA4 SMARCB1, ARID1A, ARID1B, and PBRM1 in 477 adenocarcinomas of the stomach and gastroesophageal junction." (PMID 34359794, 2021). "Further investigation demonstrated that SMARCA4 played important roles in cell proliferation as evident from its upregulation in human IPF lung tissue and its downregulation in adenocarcinoma NCI-H522 cells." (PMID 32258117, 2020). "For NSCLC, the most frequent mutations are found in the chromatin remodeling factors including SMARCA4/BRG1, and the H3K36 histone methyltransferase SETD2, in 6% and 9% of adenocarcinomas, respectively." (PMID 28672805, 2017). "Unlike SMARCA4-UT, NSCLC with SMARCA4 deficiency usually shows cohesive fragments of malignant cells with at least focal adenocarcinoma or squamous cell differentiation, which can be confirmed with TTF-1, p63/p40, or keratin IHC stains." (PMID 40406754, 2025). "Currently, there is no specific treatment recommendation for subtypes of adenocarcinomas or SMARCA4-UT." (PMID 39001412, 2024). "Aberrant SMARCA4 protein expression was reported to be frequently observed in 49% (25/51) of solid-type poorly differentiated adenocarcinomas and nonsolid-type poorly differentiated adenocarcinomas (7.5%, 3/40)." (PMID 38090508, 2023). "SMARCA2 and/or its binding protein SMARCA4 is absent or disrupted in approximately 17% of all human adenocarcinomas." (PMID 23668334, 2013). "Aberrant SMARCA4 protein expression was more common in solid-type poorly differentiated adenocarcinomas (49%, 25/51) than in nonsolid-type poorly differentiated adenocarcinomas (7.5%, 3/40), this report did not describe the complete or partial loss of SMARCA4 protein expression." (PMID 38877473, 2024). "Depletion of SMARCA4, but not of SMARCA2, significantly reduced proliferation of the adenocarcinoma cell line LNCaP and the LNCaP-derived androgen-independent CRPC-Adeno cell line C4-2, in line with previous findings." (PMID 33144576, 2020).
infection (13 papers, 2012 to 2025). The state of being infected such as from the introduction of a foreign agent such as serum, vaccine, antigenic substance or organism. "SMARCA4 inhibitors also inhibit infection of a remdesivir-resistant SARS-CoV-2, highlighting the utility for new antiviral drug classes." (PMID 36894709, 2023). "In this study, we observed that RSV also induces SMARCA4 expression and explored its role in the cellular response to infection." (PMID 33732255, 2021). "WT and SMARCA4 complex-depleted cells in the absence or presence of pRSV infection were assayed for SMARCA4, BRD4 and RNA Pol II binding to the proximal MMP9 promoter." (PMID 33732255, 2021). "Finally, inhibition of mSWI/SNF ATP-dependent chromatin remodeling activity using three different SMARCA4/2-specific orally bioavailable small-molecule inhibitors and degraders attenuates ACE2 expression and reduces infection of numerous SARS-CoV-2 variants." (PMID 36894709, 2023). "At day 9 post-infection, network 2 illustrated interactions between several miRNAs and genes such as CTNNB1, SMARCA4, and ESR1." (PMID 41157560, 2025). "Wild type (WT) hSAECs were infected with sucrose-purified RSV [multiplicity of infection (MOI) =1] for 24 h, and SMARCA4/Brg1 transcripts were quantified by Q-RT-PCR." (PMID 33732255, 2021).
cardiovascular diseases (8 papers, 2021 to 2025). "Therefore, SMARCA4 and SMARCA2 are not ideal targets for cardiovascular disease treatment." (PMID 38247859, 2024).
CNS tumors (6 papers, 2016 to 2025). "MiR-21 is upregulated in a variety of CNS tumors, possibly because of its role in targeting tumor suppressors Acidic Nuclear Phosphoprotein 32 Family, Member A (ANP32A) and SWI/SNF-related, Matrix-associated, Actin-dependent Regulator Chromatin group A (SMARCA4)." (PMID 26904099, 2016). "According to the 2016 WHO Classification of Tumors of the CNS, AT/RT is defined as having specific genetic alterations in the INI1/SMARCB1/hSNF5, or rarely, in the SMARCA4/BRG1 genes." (PMID 33384656, 2020).
genetic disorder (5 papers, 2014 to 2023). "Mutations in Coffin–Siris also occur in SMARCB1 (BAF47), SMARCA4 (BRG1), SMARCE1, ARID1A, and ARID1B, which attests to the role of the SWI/SNF complex in this genetic disorder." (PMID 25774356, 2014). "This genetic disorder is caused by de novo mutations of ARID1A (CSS2; 1p36.11; MIM 614607), ARID1B (CSS1; 6q25.3; MIM 135900), DPF2 (CSS7; 11q13.1; MIM 618027), SMARCA4 (CSS4; 19p13.2; MIM 614609), SMARCB1 (CSS3; 22q11.23; MIM 614608) or SMARCE1 (CSS5; 17q21.2; MIM 616938) genes." (PMID 32916978, 2020).
cardiac disease (2 papers, 2022 to 2024). "In this larger validation cohort, BRG1/SMARCA4 protein expression was significantly greater in HCM tissues compared to other cardiac disease and control groups (p < 0.0001)." (PMID 35581268, 2022).
hematologic malignancies (2 papers, 2023 to 2024). "Indeed, as discussed in previous sections, many SWI/SNF subunits (including the widely mutated ARID1A and SMARCA4) play specific roles in the differentiation of lymphoid and myeloid lineages and in the maintenance of some hematological malignancies." (PMID 36810086, 2023). "At least, that seems to be the case for the regulation of SMARCA4 by miR-155 in some hematological malignancies." (PMID 36810086, 2023). "In hematological malignancies, most of the SWI/SNF subunit-targeting therapies described so far are based on small inhibitors targeting either SMARCA4/SMARCA2 or BRD9." (PMID 36810086, 2023). "Additionally, a novel SMARCA4/SMARCA2 inhibitor, FHD-286, is being evaluated in a phase 1 dose escalation study in patients with advanced hematologic malignancies (ClinicalTrials.gov ID NCT04891757)." (PMID 39439958, 2024).
neurodegenerative disease (2 papers, 2010 to 2023). A disorder of the central nervous system characterized by gradual and progressive loss of neural tissue and neurologic function. "Importantly, all of these synaptic regulators (Nos1, Lrp8, Argef2, Sema5b) and other significantly altered splice variants (e.g., Adipor2, Mapk14, Smarca4, Sort1, Mapt) have been linked to AD and other neurodegenerative diseases." (PMID 37819053, 2023).
epithelial neoplasms of the (1 paper, 2024). "WHO has classified SMARCA4-UT as “other epithelial neoplasms of the lung” in 2021 to increase focus on SMARCA4-UT." (PMID 38347129, 2024).
gastrointestinal tumors (1 paper, 2025). "In the literature review, we identified only 4 previously reported cases of SMARCA4-deficient gastrointestinal tumors with sarcomatoid components that had a definitive pathological diagnosis." (PMID 41170461, 2025). "Reported cases: clinicopathologic features of SMARCA4-deficient gastrointestinal tumors with sarcomatoid components." (PMID 41170461, 2025).
head and neck tumors (1 paper, 2023). "In the latest WHO classification of head and neck tumors, NUT midline, SMARCA4-deficient, and SMARCB1-deficient SNCs have been recognized as separate entities." (PMID 36937407, 2023).
hematopoietic cancer (1 paper, 2023). "Across a wide variety of hematological and non-hematological cancers, mutations in SMARCA4 are usually missense and heterozygous, and many of them have been proven to be dominant negative in at least some cellular contexts." (PMID 36810086, 2023). "Indeed, it has been shown that several hematopoietic cancer cell lines are exquisitely sensitive to dual SMARCA4/SMARCA2 catalytic inhibitors." (PMID 36810086, 2023).
SMARCA4 also shares sentences with these, for which no sentence is quoted: cardiac hypertrophy (26 papers); neurodevelopmental disorder (10); adenoma (8); prostate tumors (8); synovial sarcoma (8); ovarian clear cell cancer (6); steatosis (6); endothelial dysfunction (5); aneurysm (4); astrocytoma (4); CHARGE syndrome (4); cholangiocarcinoma (4); Cirrhosis (4); cutaneous melanoma (4); diabetes (4); embryonal tumors (4); fibrosis (4); germ cell tumors (4); head and neck cancer (4); hypertrophic cardiomyopathy (4); neuroendocrine tumors (4); non-alcoholic steatohepatitis (4); sinonasal undifferentiated carcinoma (4); skin cancer (4); acute liver failure (3); adenoid cystic carcinoma (3); anaplastic large cell lymphoma (3); Autoimmunity (3); B cell lymphomas (3); cataract (3).
A further 223 diseases each share a sentence with SMARCA4 in 3 papers or fewer.